ZHX2 (zinc fingers and homeoboxes 2)
Description:
Acts as a transcriptional repressor. Represses the promoter activity of the CDC25C gene stimulated by NFYA. May play a role in retinal development where it regulates the composition of bipolar cell populations, by promoting differentiation of bipolar OFF-type cells (By similarity). In the brain, may promote maintenance and suppress differentiation of neural progenitor cells in the developing cortex (By similarity).
Synonyms: AFR1; KIAA0854; RAF
Tractability: PROTAC: UniProt records ubiquitination sites on it; ubiquitination databases record sites on it; its protein half-life has been measured.
Gene: Protein-coding gene on chromosome 8 (122,781,311 to 122,974,514, forward strand). Ensembl gene ENSG00000178764.
Subcellular location: Nucleus
Subcellular location (Human Protein Atlas): Nucleoplasm
Gene Ontology:
Molecular function: identical protein binding; protein binding; protein heterodimerization activity; protein homodimerization activity; DNA-binding transcription factor activity, RNA polymerase II-specific; DNA binding
Biological process: negative regulation of DNA-templated transcription; negative regulation of transcription by RNA polymerase II; regulation of transcription by RNA polymerase II; retinal bipolar neuron differentiation
Cellular component: nucleoplasm; nucleus; chromatin
Genetic constraint (gnomAD): Loss-of-function variants: 6 observed, 22.92 expected, observed/expected ratio (o/e) 0.26, 90% interval 0.14 to 0.52. The upper end of that interval is the gene's LOEUF score, 0.52, which puts it in group 2 of 6, group 1 being the genes least tolerant of losing a copy. Missense variants: 908 observed, 1,148.8 expected, observed/expected ratio (o/e) 0.79, 90% interval 0.75 to 0.83. Synonymous variants: 434 observed, 460.09 expected, observed/expected ratio (o/e) 0.94, 90% interval 0.87 to 1.02.
Homologues: Orthologues: chimpanzee ZHX2 (99% identical), macaque ZHX2 (99% identical), dog ZHX2 (92% identical), pig ZHX2 (91% identical), guinea pig ZHX2 (89% identical), mouse Zhx2 (87% identical), rat Zhx2 (86% identical), rabbit ZHX2 (85% identical), tropical clawed frog zhx2 (56% identical), zebrafish zhx2a (43% identical), zebrafish zhx2b (11% identical). Paralogues in human: ZHX1 (38% identical), ZHX3 (32% identical), HOMEZ (10% identical).
Diseases named in the same sentence as ZHX2 in open-access papers:
ZHX2 is named in the same sentence as 68 diseases in open-access papers, as found by Europe PMC text mining. Sharing a sentence is not in itself a finding about the gene and the disease. The quoted sentences say what the papers report.
hepatocellular carcinoma (20 papers, 2013 to 2025). A malignant tumor that arises from hepatocytes. "Therapeutically, the transfer of ZHX2-deficient NK cells inhibited hepatoma homograft tumor growth and metastasis." (PMID 36232466, 2022). "As a regulator of the oncofoetal genes alpha foetal protein (AFP) and glypican-3 (GPC3), ZHX2 inhibits the development of hepatocellular carcinoma." (PMID 35151335, 2022). "Overexpression of ZHX2 promotes the expression of miR-155, which in turn inhibits the growth of hepatocellular carcinoma cells." (PMID 33542193, 2021). "In hepatocellular cancer, the expression level of ZHX2 in the nucleus was significantly decreased and correlated with tumor differentiation." (PMID 33837660, 2021). "ZHX2 has been reported to regulate the replication of hepatitis B virus, decrease hepatitis B viral load and inhibit hepatocellular cancer progression." (PMID 33837660, 2021). "Other studies also discovered that ZHX2 is underexpressed in hepatocellular carcinoma tissues and cells and exerted a transcriptional repression role." (PMID 33542193, 2021). "In hepatocellular carcinoma, NF‐YA repressed by ZHX2 inhibited the activation of MDR1 transcription and, in doing so, enhances the effects of chemotherapeutics." (PMID 32954681, 2020). "Recently, it has been shown that the transcription factor, zinc fingers and homeoboxes 2 (ZHX2), functions as a tumor suppressor during the development of hepatocellular cancer and lymphoma." (PMID 31035491, 2019). "The roles played by ZHX family members in proliferation was first revealed by studies on ZHX2, which was found to suppress the proliferation of hepatocellular carcinoma cells by inducing cell cycle arrest at G1." (PMID 27835650, 2016). "The expressions of zinc fingers and homeoboxes 2, nuclear factor-YA, and alpha-fetoprotein mRNA in 63 hepatocellular carcinoma were detected by reverse transcriptase-polymerase chain reaction and compared with the clinical parameters of the patients." (PMID 23533382, 2013). "Furthermore, Zhx2 was found to inhibit de novo synthesis of FA and subsequent progression of hepatocellular carcinoma." (PMID 40589742, 2025). "Later studies show that ZHX2 is a tumor suppressor in hepatocellular carcinoma and lung cancer." (PMID 32780537, 2020). "Interestingly enough is the fact that during liver carcinoma, the normal transcriptional program of ZHX2 is highly altered." (PMID 29119102, 2017). "Previously, zinc finger and homeobox 2 (ZHX2) were reported to be tumor suppressors in hepatocellular carcinoma (HCC) and lymphoma." (PMID 39850947, 2024). "As a transcriptional factor and the negative regulator of alpha fetal protein (AFP), Zinc fingers and homeoboxes 2 (ZHX2) has a well-established role in protection against hepatocellular carcinoma (HCC)." (PMID 36465389, 2022). "Tumor-suppressive functions of ZHX2 were supported by the following studies, with most from hepatocellular carcinoma (HCC)." (PMID 36232466, 2022). "Identified as a transcription factor, ZHX2 inhibits the development of hepatocellular carcinoma (HCC)." (PMID 35151335, 2022). "Taking into account the fact that NFYA is the most important overall activator in the network, we can argue that under a repression of NFYA via ZHX2, the consequence will be a general inhibition of the transcriptional program, which may result for instance, in the progression of liver carcinoma." (PMID 29119102, 2017). "We previously reported the tumor suppressor function of Zinc-fingers and homeoboxes 2 (ZHX2) in hepatocellular carcinoma (HCC)." (PMID 25473899, 2015). "As the target of Zinc-fingers and homeoboxes (ZHX2), a tumor suppressor, KDM2A is negatively correlated with ZHX2 in hepatoma cells." (PMID 36797239, 2023). "Several studies have demonstrated the tumor-suppressor activities of ZHX2 in hepatocellular carcinoma (HCC) and other malignancies, but accumulating evidence has also shown that ZHX2 plays oncogenic roles in carcinogenesis and progression in various cancers." (PMID 36232466, 2022).
hepatocellular carcinoma (continued). "ZHX2 was initially found as a negative regulation gene of AFP and was subsequently demonstrated to have a tumor suppressive role in hepatocellular cancer." (PMID 33837660, 2021). "Additionally, ZHX2 was reported to have tumor suppressor activity in hepatocellular carcinoma (HCC), by repressing cyclin A, E, and multidrug resistance 1 (MDR1) expression." (PMID 34779768, 2021). "In a study of liver cancer, researchers found that ZHX2 can repress CCNA2 transcription by binding the promoter regions of CCNA2, thereby inhibiting the proliferation of hepatoma cells." (PMID 31956366, 2020). "ZHX2 can enhance the nuclear translocation of NF‐κB and promote tumorigenesis in renal cell carcinoma, however, studies also show that ZHX2 is a tumor suppressor in lung cancer and hepatocellular carcinoma, therefore it is still unknown that the role of ZHX2 in myeloma." (PMID 32780537, 2020). "In hepatocellular carcinoma and gastric cancer, the expression of ZHX1 was lower than in normal tissues, and the nuclear expression of ZHX2 was diminished in HCC." (PMID 28152006, 2017). "Our previous studies have demonstrated reduced ZHX2 expression in hepatocellular carcinoma (HCC)." (PMID 23533382, 2013). "Zinc fingers and homeoboxes 2 can regulate alpha-fetoprotein expression via the interaction with nuclear factor-YA in human hepatocellular carcinoma and may be used as an adjuvant diagnostic marker for alpha-fetoprotein-negative hepatocellular carcinoma." (PMID 23533382, 2013).
clear cell renal cell carcinoma (10 papers, 2020 to 2025). "Conversely, the VHL substrate transcription factor ZHX2 has been identified as an oncogenic driver in VHL-deficient clear cell renal cell carcinoma (ccRCC)." (PMID 39850947, 2024). "In contrast, the VHL substrate transcription factor zinc fingers and homeoboxes 2 (ZHX2) have been identified as the oncogenic drivers in VHL-deficient clear cell renal cell carcinoma (RCC)." (PMID 39850947, 2024). "The VHL substrate transcription factor zinc fingers and homeoboxes 2 (ZHX2) have been identified as an oncogenic driver in VHL-deficient clear cell renal cell carcinoma (RCC)." (PMID 39850947, 2024). "ZHX2 is widely expressed and participates in many types of cancers, such as gastric cancer, lung cancer and clear cell renal cell carcinoma." (PMID 35151335, 2022). "However, recent studies have suggested ZHX2 as an oncogene in clear cell renal cell carcinoma (ccRCC) and triple-negative breast cancer (TNBC)." (PMID 36465389, 2022). "ZHX2 can drive tumorigenesis in clear cell renal cell carcinoma (ccRCC)." (PMID 36232466, 2022). "Moreover, ZHX2 was demonstrated to be highly expressed in renal clear cell carcinoma and to activate the nuclear factor‐kappa B pathway via epigenetic modification to promote cancer cell proliferation and migration." (PMID 33837660, 2021). "Finally, ZHX2 is a transcriptional repressor which promotes clear cell renal cell carcinoma soft-agar and tumor growth." (PMID 34072264, 2021). "However, a report showed that ZHX2 promotes the migration of clear cell renal carcinoma cells." (PMID 35151335, 2022). "A study on clear cell renal cancers (ccRCC) based on an online database showed that both ZHX1 and ZHX3 expression levels were downregulated, while ZHX2 was upregulated." (PMID 36232466, 2022).
liver cancer (9 papers, 2014 to 2023). An epithelial or non-epithelial malignant neoplasm that arises from the liver. "Studies have shown that ZHX2 is negatively correlated with the expression of MDR1 in liver cancer tissue and that ZHX2 can inhibit the expression of MDR1 at the transcriptional level and promote the sensitivity of liver cancer to chemotherapy drugs." (PMID 37563132, 2023). "In liver cancer tissues, the expression of ZHX2 is significantly reduced owing to the methylation of the ZHX2 promoter, which is positively correlated with the degree of tumor differentiation." (PMID 37563132, 2023). "As a liver cancer suppressor, ZHX2 expression is significantly decreased in tumor tissue from HBV-positive HCC patients and liver from HBV transgenic mice." (PMID 36465389, 2022). "recently showed that whole body Zhx2 knockout (Zhx2KO) leads to dramatically reduced liver cancer in DEN-induced HCC mouse model, indicating the oncogenic role of ZHX2 in DEN-induced liver tumor model." (PMID 36465389, 2022). "ZHX2 expression levels have been significantly reduced in liver cancer stem cells (CSCs) from different origins." (PMID 36232466, 2022). "Originally, ZHX2 was found to be a key transcriptional repressor for the alpha-fetoprotein regulator 1 (Afr1), which is an important oncogene in liver cancer." (PMID 34779768, 2021). "Then ZHX2 levels were experimentally increased or decreased in several liver cancer cell lines, followed by treatment with CDDP and ADM." (PMID 25473899, 2015). "In conclusion, the results provide a basis for further clinical research in combining ZHX2 and chemotherapeutic agents to treat liver cancer." (PMID 25473899, 2015). "Therefore, identifying the role of ZHX2 in regulating the I-125-induced apoptosis of liver cancer cells will further demonstrate the tumor-suppressive role of ZHX2 in HCC." (PMID 37563132, 2023). "Mechanistic studies demonstrated that tumor inhibition was through the suppression of Cyclins A and E via a direct binding between ZHX2 and the promoter domain of Cyclins A and E. The inverse correlation between ZHX2 and Cyclins A and E was further detected from liver cancer tissues." (PMID 36232466, 2022). "However, it has been reported that the ZHX2 protein was overexpressed in liver cancer tissues, and that its upregulation expression was related to poor differentiation and cancer metastasis, suggesting an oncogene role of ZHX2 in HCC." (PMID 36232466, 2022). "Conclusively, these data provided a novel mechanism for ZHX2 inhibiting HCC progression, and targeting the ZHX2/SREBP1c axis could be a novel treatment method of liver cancer." (PMID 36232466, 2022). "Taken together, our data identify MDR1 as a new target of the tumor suppressor ZHX2 and suggest that ZHX2 maybe a novel target for the treatment of liver cancer." (PMID 25473899, 2015). "Similarly, ZHX2 (zinc fingers and homeoboxes 2) represses transcription of several genes including cyclin E and cyclin A, but is strongly deregulated in liver cancer due to hypermethylation of its promoter." (PMID 24419005, 2014). "Based on the function of ZHX2 as a transcriptional repressor and its known interaction with NF-YA, we hypothesized that ZHX2 might inhibit MDR1 expression in liver cancer cells, resulting in reduced efflux of chemotherapeutic drugs and subsequent increased sensitivity to these agents." (PMID 25473899, 2015). "It is worth noting that the putative ZHX2-binding motif is also located in the previously reported ZHX2 target genes, such as Cyclin E and KDM2A, which are involved in liver cancer progression." (PMID 37980429, 2023). "The most downregulated gene was ZHX2 (-8.4 fold), which was shown to promote AFP secretion leading to activation in liver cancer." (PMID 26085845, 2014). "ZHX2 and MDR1 mRNA levels were compared in several liver cancer cell lines." (PMID 25473899, 2015).
breast carcinoma (8 papers, 2018 to 2023). "Low ZHX2 is associated with poor prognosis in chronic lymphocytic leukemia and multiple myeloma (MM), while higher ZHX2 mRNA correlates with better overall survival in patients with breast cancer and thyroid cancer." (PMID 36465389, 2022). "To further explore the role of ZHX2 in breast cancer lung metastasis, we intravenously injected 5-week-old female athymic nude mice with vector control, ZHX2 deletion or the ZHX2 expression restored MDA-MB-231 cells." (PMID 37460540, 2023). "The data showed that the mRNA expression of CDH1 negatively correlated with that of ZHX2 in breast cancer." (PMID 37460540, 2023). "Lastly, to further investigate the relevance of CDH1 and ZHX2 in breast cancer patients, we first examined their mRNA levels in breast cancer (n = 148) from the gene expression database available through METABRIC." (PMID 37460540, 2023). "Given this, we generated a series of TNBC breast cancer cell lines where we depleted endogenous ZHX2 expression and restored with exogenous shRNA-resistant ZHX2 WT or mutant versions (D489A, R491A, E579A, R581A, K582, R674A, E678A, or R680A)." (PMID 34779768, 2021). "(C) The percentage of ZHX2 amplification of different breast cancer subtypes in several breast cancer datasets." (PMID 34779768, 2021). "Since TNBC had the highest ZHX2 amplification rate in all breast cancer subtypes, we decided to focus on TNBC for this current study." (PMID 34779768, 2021). "Analysis of copy number across different cancer types from The Cancer Genome Atlas (TCGA) showed that ZHX2 is amplified in various cancers, including ovarian cancer (~40%) and breast cancer (~15%)." (PMID 34779768, 2021). "Detailed analyses of several breast cancer patient datasets also revealed that TNBC had the highest ZHX2 amplification rate in all breast cancer subtypes." (PMID 34779768, 2021). "It is also important to point out that ZHX2 is located on 8q24, a genomic region that is frequently amplified in various cancers including breast cancer." (PMID 34779768, 2021). "In addition, copy number analysis showed that ZHX2 gene is amplified in various cancers, including ovarian cancer (~40%) and breast cancer (~15%)." (PMID 36465389, 2022). "Both ZHX2 and ZHX3 expressions were remarkably reduced in TNBC tissues, and a high mRNA expression of ZHX2 and ZHX3 were closely associated with a better prognosis of breast cancer patients, especially in luminal A subtype breast cancer." (PMID 36232466, 2022). "Interestingly, all breast cancer cell lines displayed relatively higher ZHX2 protein levels compared to HMLE or MCF-10A." (PMID 34779768, 2021). "Although ZHX2 and c-Myc displayed similar amplification and expression manner in breast cancer." (PMID 34779768, 2021). "We found a significant correlation between copy number and gene expression, suggesting that ZHX2 amplification may be at least partially responsible for its overexpression in breast cancer." (PMID 34779768, 2021). "Indeed, ZHX2 is amplified in several cancers, including breast cancer, ovarian cancer, and prostate cancer." (PMID 34779768, 2021). "We further explored the effect of ZHX2 expression on breast cancer patient survival." (PMID 34779768, 2021). "In addition, the mRNA expression of ZHX2 and ZHX3 were also positively associated with the estrogen receptor and progesterone receptor, but ZHX2 mRNA expression was inversely correlated with HER2 in breast cancers." (PMID 36232466, 2022). "Since ZHX2 was similarly reported as an oncogene in ccRCC and preferentially upregulated the transcription of downstream genes, we focused on the 3969 ZHX2 positively regulated genes (downregulated following ZHX2 silencing by shRNA) as these genes may be more relevant in breast cancer." (PMID 34779768, 2021). "Such as CMSS1 and ZHX2 in uterine cancer, OSBPL8, FAM214A in breast cancer, TPT1, GPRIN3, and VAV3 in pancreatic cancer." (PMID 37024957, 2023).
breast carcinoma (continued). "In addition, it is unclear whether ZHX2 also acts as a pVHL target in breast cancer." (PMID 34779768, 2021). "ZHX2 overexpression (Affymetrix probe 236169_at) correlates with worse survival in TNBC but not in other breast cancer subtypes." (PMID 34779768, 2021).